BMP7 (bone morphogenetic protein 7)
Diseases named in the same sentence as BMP7 in open-access papers (continued):
Sharing a sentence is not in itself a finding about the gene and the disease.
liver fibrosis (40 papers, 2012 to 2026). "In vitro, upregulation of BMP9 enhanced damage to hepatocytes and promoted liver fibrosis, whereas in vivo, BMP7 was associated with reduced liver fibrosis." (PMID 32561790, 2020). "In all cases, the therapeutic effect against hepatic fibrosis was associated with an up-regulation of BMP7." (PMID 29295498, 2017). "Furthermore, to test whether BP reduces fibrosis in a BMP-7 deficient liver, an in vivo study of a zebrafish liver fibrosis model was conducted by administering TAA treatment." (PMID 27199755, 2016). "On the other hand, BMP7 overexpression reduced the fibrotic effects of miR-3074 in HSCs, and in liver fibrosis induced by CCl4in vivo." (PMID 40260391, 2025). "The analysis of BMP-7 expression in samples from patients with liver fibrosis and cirrhosis revealed a consistent pattern of initially increasing expression, followed by a subsequent decrease." (PMID 38275673, 2024). "Within the mouse model, the expression level of BMP-7 initially exhibited an increase, subsequently transitioning into a decrease as liver fibrosis advanced." (PMID 38275673, 2024). "Animal models and patients with liver fibrosis have also provided evidence of BMP-7’s antifibrotic effects on the liver." (PMID 38275673, 2024). "(i) While BMP-7 has long been known to have antifibrotic properties in renal and pulmonary tissues, its role in liver fibrosis is still controversial." (PMID 37915043, 2023). "Earlier studies have revealed that treating CCl4-mediated liver fibrosis mice with antisense miR-22 increases BMP7 expression, and remarkably suppresses the development of fibrosis." (PMID 37371520, 2023). "Few AAV-mediated gene therapies were conducted using transgenes hepatocyte growth factor (HGF), bone morphogenetic protein 7 (BMP7), and microRNA-19b (miRNA-19b), where all of them were confirmed to assess the resolution of liver fibrosis." (PMID 37232739, 2023). "Multiple studies have reported that bone morphogenetic protein-7 (BMP7) effectively inhibits fibrosis involving various organs, such as retinopathy, liver fibrosis, and peritoneal fibrosis." (PMID 37293506, 2023). "BMP7 treatment alleviated liver fibrosis in mice, with decreased Collagen type I and increased MMP2 expression levels." (PMID 34608249, 2021). "In the process of CCl4-induced liver fibrosis in mice, the expression of BMP7 increased first and then decreased as well as in human patients with CLD." (PMID 34440218, 2021). "BMP-7 was also studied in hepatic fibrosis using mice models where the fibrosis was induced by an injection of carbon tetrachloride (CCL4)." (PMID 32508821, 2020). "Injection of adenoviral BMP-7 promoted the reversion of liver fibrosis/cirrhosis in the CCl4-induced cirrhotic hamster model." (PMID 31151477, 2019). "Id2 is a downstream target of BMP7 which antagonizes the TGF-β1-dependent fibro-genic activity in liver fibrosis and pulmonary myofibroblastic cells." (PMID 31803053, 2019). "In another animal model of liver fibrosis induced by administering porcine serum it was shown that recombinant human (rh) BMP7 significantly reduces collagen deposition." (PMID 31547567, 2019). "Oral administration of recombinant adeno-associated virus carrying BMP-7 in mice led to an increased circulating BMP-7 concentration and resulted in amelioration of CCl4-induced liver fibrosis and HSC activation." (PMID 31151477, 2019). "And in other animal models like thioacetamide- or repeated intraperitoneal injection of porcine serum-induced liver fibrosis in rats, ectopic expression of BMP-7 can also inhibit the fibrogenic progress." (PMID 31151477, 2019). "Our most recent study focused on bone morphogenetic protein 7 (BMP-7)/Smad signaling to determine its biochemical mechanisms involved in attenuating liver fibrosis." (PMID 29402324, 2018).
liver fibrosis (continued). "In the liver, adenovirus mediated ectopic expression of BMP7 suppresses thioacetamide (TAA)-induced hepatic fibrosis in rats, reducing the expression of α-smooth muscle actin (αSMA), type I collagen and hydroxyproline content." (PMID 29295498, 2017). "BMP7 demonstrated to inhibit liver fibrosis and suppress activation of HSCs, via downregulation of TGF-β1 and α-SMA." (PMID 28769795, 2017). "To demonstrate that BP suppressed liver fibrosis by regulating BMP-7, we first developed TAA-induced liver fibrosis in zebrafish." (PMID 27199755, 2016). "Conversely, BMP-7 can attenuate and even prevent the level of hepatic fibrosis in rats through inhibition of the expression of TGF-β127." (PMID 27853271, 2016). "In summary, we demonstrated that BP reduced EMT by regulating BMP-7 in order to ameliorate liver fibrosis." (PMID 27199755, 2016). "In the present study, significantly less α-SMA and TGF-β1 and more BMP-7 and E-cadherin was expressed in the alendronate sodium-treated group and the controls than in the CCl4-induced mouse liver fibrosis model group (P<0.001)." (PMID 23251277, 2013). "In this study, we demonstrate that BMP-7 induces MET through Snail1 in rat liver fibrosis cells (post-EMT)." (PMID 23226767, 2012). "Administration of BMP-7 in pharmacological doses attenuates the development of kidney fibrosis and liver fibrosis." (PMID 22973518, 2012). "Significantly more BMP-7 and less Snail mRNA were expressed in the hepatic fibrosis model group than in the controls (P<0.001)." (PMID 23226767, 2012). "Moreover, the therapeutic efficacy of UC cord MSCs Exo loaded with bone morphogenetic protein 7 was significantly superior to that of unmodified or negative control exosomes in reversing hepatic stellate cell activation and attenuating liver fibrosis." (PMID 41527491, 2026). "Similarly, EVs from hucMSCs loaded with the anti-fibrotic bone morphogenetic protein 7 (BMP7) showed a better therapeutic effect in hepatic fibrosis relative to untreated EVs." (PMID 39767572, 2024). "After the administration of recombinant BMP-7, there was a suppressed progression of liver fibrosis and an improved liver function, partly due to downregulation of type I collagen, α-sma, and TIMP2 and up-regulation of MMP-2 with the suppression of expression of TGF-β." (PMID 32508821, 2020). "Inhibition of EndMT by BMP-7 improved liver fibrosis in mice." (PMID 31718044, 2019). "In liver fibrosis, the involvement of BMP-7 has only recently been suggested." (PMID 31151477, 2019). "We also showed that Cpd861 could attenuate liver fibrosis through upregulation of BMP-7/Smad signaling." (PMID 29402324, 2018). "In the classic CCl4-induced liver fibrosis mouse model, BMP7 antifibrotic effects have been proposed to rely on its crosstalk with EGFR and TGF-β1, by suppressing their expression and inhibiting activation of EGFR and abolishing the accumulation of hepatocyte-derived fibroblasts via EMT." (PMID 29295498, 2017). "Likewise, BMP7 reduces TGF-β levels in liver in a rat model of liver fibrosis mediated by injection of porcine serum." (PMID 29295498, 2017). "Additionally, in efforts to define regulators of BMP7/Smad signaling, it was demonstrated that a herbal compound was effective in alleviating hepatic fibrosis via enhancements in p-Smad1/5/8 levels and BMP7 antifibrotic signaling." (PMID 28620300, 2017). "Exogenous BMP-7 exerts an anti-fibrogenic effect in hepatic fibrosis model rats." (PMID 27863390, 2016). "Finally, in the in vivo study, BP treatment of liver fibrosis was reduced by Bmp7 knockdown in zebrafish, suggesting that BP leads to the reduction of liver fibrosis, which also depends on BMP-7 induction." (PMID 27199755, 2016). "These opposite effects on the protein and mRNA levels of TGF-β1 and BMP-7 suggested that DWYG treatment could prevent CCl4-induced liver fibrosis in rats through recovering the ratio of TGF-β1/BMP-7." (PMID 25345787, 2014).
liver fibrosis (continued). "Therefore, miR-22 possibly enhances liver fibrosis development by suppressing BMP7." (PMID 37371520, 2023). "Furthermore, in the Schistosoma japonicum-induced liver fibrosis mouse model, administration of recombinant BMP-7 intraperitoneally significantly decreased the degree of collagen deposition and the expression of α-SMA in the liver, measured by Masson’s staining and α-SMA staining." (PMID 31151477, 2019). "hAECs are able to diminish liver fibrosis via a blockade of TGF-β and PDGF signaling, and an induced secretion of anti-fibrotic factors PGE-2, bone morphogenetic protein-7 (BMP-7), and IL-10." (PMID 37626924, 2023). "Another study on the role of TGF-β in liver fibrosis utilized a mouse model to investigate the relationship between TGF-β and another member of the TGF family, BMP7." (PMID 34909658, 2021). "Studies have shown that TGFβ1 crosstalks with BMP7, BMP9, and SMAD1/5/8, all of which can affect liver fibrosis 45-47." (PMID 33754025, 2021). "These authors observed that mice with induced liver fibrosis had upregulated levels of TGF-β and Smad3, and downregulated BMP7 and Smad1/5/8." (PMID 34909658, 2021). "Thus, exogenous BMP7 may be used as an anti-liver fibrosis drug." (PMID 34440218, 2021). "Since both endoglin and BMP7 are expressed in HSC, it would be interesting to know if a similar effect is accomplished in this population during liver fibrosis." (PMID 29295498, 2017). "The BP-reduced liver fibrosis was abolished by BMP-7 knockdown, suggesting that BP suppressed TAA induced liver fibrosis through BMP-7 in zebrafish." (PMID 27199755, 2016). "We observed that the downregulated expression of TGF-β was partially recovered in BMP-7 knockdown cells, leading to an increase in EMT, which has been reported to promote liver fibrosis." (PMID 27199755, 2016). "However, as BMP-7 levels may also change under other pathological conditions such as hepatic fibrosis, the results may be misinterpreted in patients suffering from these diseases, thereby interfering with the diagnostic specificity of the stage of kidney injury." (PMID 25790348, 2015). "Treatment with Diwu Yanggan (DWYG) significantly decreased the hepatic hydroxyproline content and degree of CCl4-induced liver fibrosis in rats and stimulated MET in the fibrotic liver through inhibition of the TGF-β1/BMP-7 signaling pathway." (PMID 25897319, 2015). "DWYG demonstrates therapeutic potential to prevent liver fibrosis by modulating the balance between EMT and MET through reducing the expression ratio of TGF-β1/BMP-7 and inhibiting the excessive activation of Hh signaling pathway." (PMID 25345787, 2014). "To date, a variety of signal transduction pathways and cytokines have been demonstrated to regulate the development of liver fibrosis, including transforming growth factor-β1 (TGF-β1), bone morphogenetic protein 7 (BMP7), and Smad." (PMID 25393508, 2014). "The underlying mechanism was associated with changes in the redox state, which remains variable in liver fibrosis, and depends on the balance between TGF-β/smad- and BMP-7-modulated mechanisms which regulate EMT and MET in multifunctional progenitors." (PMID 23251277, 2013). "In the mouse liver fibrosis model, increased expression of TGF-β1, α-SMA, N-cadherin and FSP1 mRNA was observed, but the expression of of BMP-7 and E-cadherin was reduced." (PMID 23251277, 2013). "Moreover, during liver fibrosis progression, the levels of another BMP (BMP7) showed an initial increase followed by a decline in later stages." (PMID 40260391, 2025). "Some studies have pointed out that BMP-7 induces the proliferation of hepatic stellate cells (HSCs, the main ECM-producing cells involved in liver fibrogenesis, whose excessive accumulation can lead to liver fibrosis and cirrhosis)." (PMID 37915043, 2023).
liver fibrosis (continued). "Similar findings were reported for BMP7, overexpression of which decreased the expression of collagen in HSC and suppressed fibrosis via the upregulation of Id proteins in thioacetamide-induced liver fibrosis in mice." (PMID 37798809, 2023). "EMT inducers like TGF-β and BMP-7 can be targeted for therapy; hence, we considered BP may reduce EMT, leading to the improvement in liver fibrosis." (PMID 27199755, 2016). "Considering BMP-7 as a morphogen in bone formation, and the promotion of ECM composition was also reported in other study that increase of BMP-7 concentration was correlated with liver fibrosis." (PMID 25954203, 2015). "Our data also demonstrated that DWYG could obviously decrease the expression ratio of TGF-β1/BMP-7 in CCl4-induced fibrotic liver tissue, which facilitated the reversal of EMT to MET in liver tissues and attenuated the degree of liver fibrosis." (PMID 25345787, 2014). "The redox state may remain variable in liver fibrosis and depends on the balance between TGF-β/smad- and BMP-7-modulated mechanisms that regulate EMT and mesenchymal-epithelial transition (MET) in multifunctional progenitors." (PMID 23251277, 2013). "BMP-7, another member of the TGF-β superfamily, also acts as a TGF-β antagonist and administration of BMP-7 in pharmacological doses attenuates development of kidney and liver fibrosis." (PMID 22973518, 2012). "Indeed, induction of BMP7 decreased the expression of collagen and αSMA mRNA via SMAD 1/5/8 phosphorylation in both primary cultured rat stellate cells and in human stellate cell line LX-2, and suppressed thioacetamide (TAA)-induced liver fibrosis in rats." (PMID 31547567, 2019). "Moreover, BMP-7, a member of the TGF-β surperfamily that antagonizes TGF-β1 signaling, negatively regulates TGF-β1-induced EMT in different types of organ injury, including liver fibrosis." (PMID 25345787, 2014). "There is data showing that on a model of hepatic fibrosis, the BMP-7 RNA levels in the liver are the same whether the animals are treated or not with BMP-7." (PMID 24781156, 2014).
diabetes (34 papers, 2010 to 2025). "Lower levels of BMP7 are also associated with various diseases, including osteoporosis, cardiovascular diseases and diabetes." (PMID 40076659, 2025). "Moreover, research has linked the BMP7 gene to diabetes and vascular calcification in humans, while the SPO11 gene has been linked to endothelial dysfunction resulting from exercise-induced DNA damage in horses." (PMID 39118059, 2024). "Together, our data suggest that BMP7 enhanced skin wound healing in diabetes by decreasing local inflammation and oxidative stress, which promoted a regenerative environment for collagen deposition, wound maturation, cell proliferation, and angiogenesis." (PMID 40076659, 2025). "This BMP7 effect is very important since the wounds of patients with diabetes showed to have a loose extracellular matrix in the wound bed, which impairs cellular functions such as migration and proliferation, important for wound healing progression." (PMID 40076659, 2025). "These important findings underscore recombinant human BMP7 as a novel candidate for the treatment of skin wounds in diabetes." (PMID 40076659, 2025). "The results of our study demonstrated that BMP7 reduced the diabetes-induced elevated number of T lymphocytes and pro-inflammatory M1 macrophages in wounds of diabetic mice." (PMID 40076659, 2025). "Blood glucose levels were significantly (p < 0.05, ~1.62-fold) elevated in diabetic mice as compared with the control mice, whereas the BMP-7 treatment significantly (p < 0.05, ~74%) attenuated diabetes-induced hyperglycemia." (PMID 36829889, 2023). "The increased expression of BMP-7 was noted under pitavastatin treatment in podocyte cell culture and streptozotocin-induced diabetes in Wistar rats." (PMID 36836700, 2023). "For example, in a rodent model of streptozotocin-induced diabetes, BMP-7 upregulated the inhibitor of differentiation (Id2) to reduce tubulointerstitial fibrosis." (PMID 37626268, 2023). "Since the majority of studies on BMP-7’s effect on adipose tissue and energy expenditure has been performed in the context of obesity and diabetes, some questions remain unanswered in the SLE context." (PMID 37626268, 2023). "In diabetic mice, MMP9 expression was significantly (p < 0.05) increased as compared with the control mice, whereas BMP-7 treatment significantly (p < 0.05) reduced diabetes-induced MMP9 gene expression." (PMID 36829889, 2023). "Among subjects with diabetes, the elevation of BMP-7 was significant in NFR/NA, NRF/EA, and DRF/EA groups (p < 0.001, p < 0.001, and p = 0.03 vs. control, respectively)." (PMID 36836700, 2023). "Treatment with BMP7 can significantly reduce inflammasome formation, pyroptosis, and inflammatory cytokines, subsequently improving cardiac remodeling in a diabetic heart." (PMID 36858954, 2023). "This agrees with previously reported studies showing BMP‐7 improves skeletal muscle fibrosis, atrophy, sarcopenia, and muscle dysfunction in diabetes and atherosclerosis." (PMID 36945866, 2023). "Considering these together, BMP7 can be considered an alternative therapy against diabetes-induced damage to the pancreas and kidney." (PMID 37293506, 2023). "In diabetic mice, both MuRF1 and atrogin-1 gene expressions were significantly (p < 0.05) increased as compared with the control mice, whereas BMP-7 treatment significantly (p < 0.05) reduced diabetes-induced MuRF1 and atrogin-1 gene expressions." (PMID 36829889, 2023). "In an STZ-induced animal diabetes model, BMP7 was found to protect against diabetic kidney injury, counteracting TGF/SMADs signaling." (PMID 37293506, 2023). "Bone morphogenetic protein 7 (BMP-7), a drug commonly used to treat patients with osteoporosis, was recently found to alleviate diabetes-induced inflammation-mediated pyroptosis, sarcopenia, and adverse muscle remodeling." (PMID 35406642, 2022).